MAP3K7 (mitogen-activated protein kinase kinase kinase 7)
Description:
Serine/threonine kinase which acts as an essential component of the MAP kinase signal transduction pathway. Plays an important role in the cascades of cellular responses evoked by changes in the environment. Mediates signal transduction of TRAF6, various cytokines including interleukin-1 (IL-1), transforming growth factor-beta (TGFB), TGFB-related factors like BMP2 and BMP4, toll-like receptors (TLR), tumor necrosis factor receptor CD40 and B-cell receptor (BCR). Once activated, acts as an upstream activator of the MKK/JNK signal transduction cascade and the p38 MAPK signal transduction cascade through the phosphorylation and activation of several MAP kinase kinases like MAP2K1/MEK1, MAP2K3/MKK3, MAP2K6/MKK6 and MAP2K7/MKK7. These MAP2Ks in turn activate p38 MAPKs and c-jun N-terminal kinases (JNKs); both p38 MAPK and JNK pathways control the transcription factors activator protein-1 (AP-1). Independently of MAP2Ks and p38 MAPKs, acts as a key activator of NF-kappa-B by promoting activation of the I-kappa-B-kinase (IKK) core complex. Mechanistically, recruited to polyubiquitin chains of RIPK2 and IKBKG/NEMO via TAB2/MAP3K7IP2 and TAB3/MAP3K7IP3, and catalyzes phosphorylation and activation of IKBKB/IKKB component of the IKK complex, leading to NF-kappa-B activation. In osmotic stress signaling, plays a major role in the activation of MAPK8/JNK1, but not that of NF-kappa-B. Promotes TRIM5 capsid-specific restriction activity. Phosphorylates RIPK1 at 'Ser-321' which positively regulates RIPK1 interaction with RIPK3 to promote necroptosis but negatively regulates RIPK1 kinase activity and its interaction with FADD to mediate apoptosis (By similarity). Phosphorylates STING1 in response to cGAMP-activation, promoting association between STEEP1 and STING1 and STING1 translocation to COPII vesicles.
Synonyms: TAK1; MEKK7; CSCF; FMD2; TGF1a
Tractability: Small molecule: a structure with a bound ligand is known; a high-quality ligand is known; it belongs to a druggable protein family. Antibody: UniProt places it where antibodies can reach, with high confidence; its Gene Ontology location is reachable by antibodies, with high confidence; the Human Protein Atlas places it where antibodies can reach. PROTAC: it is named in the literature on targeted protein degradation; UniProt records ubiquitination sites on it; ubiquitination databases record sites on it; its protein half-life has been measured; a small molecule that binds it is known.
Target class: Kinase; Enzyme; TKL protein kinase group; TKL protein kinase TAK1 subfamily; TKL protein kinase MLK family; Protein Kinase
Chemical probes: CHEMBL2408616, NG25 (high quality), PD134626, PD134627, PD134628, PD134629, Takinib
Gene: Protein-coding gene on chromosome 6 (90,513,573 to 90,587,093, reverse strand). Ensembl gene ENSG00000135341.
Subcellular location: Cytoplasm; Cell membrane
Subcellular location (Human Protein Atlas): Cytosol; Nuclear speckles; Plasma membrane
Pathways (Reactome):
Immune System: Activation of NF-kappaB in B cells; Alpha-protein kinase 1 signaling pathway; CLEC7A (Dectin-1) signaling; Downstream TCR signaling; FCERI mediated NF-kB activation; IRAK2 mediated activation of TAK1 complex; IRAK2 mediated activation of TAK1 complex upon TLR7/8 or 9 stimulation; Interleukin-1 signaling; JNK (c-Jun kinases) phosphorylation and activation mediated by activated human TAK1; NOD1/2 Signaling Pathway; TAK1-dependent IKK and NF-kappa-B activation; TICAM1,TRAF6-dependent induction of TAK1 complex; TRAF6-mediated induction of TAK1 complex within TLR4 complex; activated TAK1 mediates p38 MAPK activation
Signal Transduction: Ca2+ pathway; TNFR1-induced NF-kappa-B signaling pathway
Disease: SARS-CoV-2 activates/modulates innate and adaptive immune responses
Metabolism of proteins: Ub-specific processing proteases
Gene Ontology:
Molecular function: identical protein binding; kinase activity; linear polyubiquitin binding; MAP kinase activity; MAP kinase kinase kinase activity; protein binding; protein serine kinase activity; protein serine/threonine kinase activity; receptor tyrosine kinase binding; scaffold protein binding; MAP kinase kinase kinase kinase activity; ATP binding; DNA-binding transcription factor binding; histone kinase activity; magnesium ion binding; MAP kinase kinase activity; protein kinase activity; protein kinase binding; protein serine/threonine kinase binding; signaling receptor binding; transcription coactivator binding; type II transforming growth factor beta receptor binding; ubiquitin protein ligase binding
Biological process: canonical NF-kappaB signal transduction; defense response to bacterium; I-kappaB phosphorylation; inflammatory response; interleukin-1-mediated signaling pathway; interleukin-17A-mediated signaling pathway; interleukin-33-mediated signaling pathway; JNK cascade; MAPK cascade; p38MAPK cascade; positive regulation of canonical NF-kappaB signal transduction; positive regulation of interleukin-2 production; positive regulation of JUN kinase activity; positive regulation of non-canonical NF-kappaB signal transduction; positive regulation of T cell cytokine production; regulation of MAPK cascade; stress-activated MAPK cascade; toll-like receptor 4 signaling pathway; anoikis; cytoplasmic pattern recognition receptor signaling pathway; Fc-epsilon receptor signaling pathway; immune response; MyD88-dependent toll-like receptor signaling pathway; nucleotide-binding domain, leucine rich repeat containing receptor signaling pathway; positive regulation of macroautophagy; and 25 more
Cellular component: ATAC complex; cytoplasm; cytosol; nucleus; plasma membrane; serine/threonine protein kinase complex; endosome membrane; postsynaptic density
Genetic constraint (gnomAD): Loss-of-function variants: 13 observed, 52.1 expected, observed/expected ratio (o/e) 0.25, 90% interval 0.16 to 0.4. The upper end of that interval is the gene's LOEUF score, 0.4, which puts it in group 1 of 6, group 1 being the genes least tolerant of losing a copy. Missense variants: 360 observed, 543.73 expected, observed/expected ratio (o/e) 0.66, 90% interval 0.61 to 0.72. Synonymous variants: 175 observed, 183.38 expected, observed/expected ratio (o/e) 0.95, 90% interval 0.84 to 1.08.
Homologues: Orthologues: chimpanzee MAP3K7 (100% identical), dog MAP3K7 (100% identical), macaque MAP3K7 (100% identical), pig MAP3K7 (99% identical), mouse Map3k7 (99% identical), rat Map3k7 (99% identical), rabbit MAP3K7 (99% identical), guinea pig MAP3K7 (98% identical), tropical clawed frog map3k7 (89% identical), zebrafish map3k7 (71% identical). Paralogues in human: PKDCC (14% identical), MAP3K7CL (11% identical).
Diseases named in the same sentence as MAP3K7 in open-access papers:
MAP3K7 is named in the same sentence as 99 diseases in open-access papers, as found by Europe PMC text mining. Sharing a sentence is not in itself a finding about the gene and the disease. The quoted sentences say what the papers report.
prostate carcinoma (19 papers, 2012 to 2025). A carcinoma that arises from epithelial cells of the prostate gland. "MAP3K7 is a key gene in prostate cancer, and MAP3K7 exon 12 splicing is associated with epithelial properties of prostate cancer cells." (PMID 31478829, 2019). "For instance, in prostate cancer MAP3K7 deletion is associated with an advanced tumor stage, lymph node metastasis and an early biochemical recurrence, and suppression of MAP3K7 has been shown to promote tumorigenesis." (PMID 29914415, 2018). "In contrast, other works point to MAP3K7 as a tumor suppressor; deletion of the MAP3K7 gene is significantly associated with high-grade prostate cancer and its loss increased proliferation, migration, and invasion in vitro." (PMID 25889255, 2015). "However, additional MAP3K7 loss completely rescued this effect and promoted prostate cancer progression." (PMID 36776288, 2023). "Nevertheless, better understanding their interactions and underlying mechanisms might provide novel therapeutic strategies for MAP3K7/CHD1 loss prostate cancer." (PMID 36776288, 2023). "They found that loss of either MAP3K7, a kinase involved in inflammatory signaling, or CHD1, a chromatin-remodeling factor, rendered previously resistant prostate cancer cells highly susceptible to VSV infection and oncolysis." (PMID 41294689, 2025). "Along the same line, Jillson and colleagues showed that co-suppression of MAP3K7 and CHD1 causes androgen-independent growth of prostate cancer cells and promotes resistance to AR inhibitor enzalutamide." (PMID 36776288, 2023). "CHD1 depletion reduced cell proliferation, invasiveness, and tumor growth of PTEN-deficient cancer cells; while loss of MAP3K7 and CHD1 coordinates to promote aggressive prostate cancer." (PMID 36776288, 2023). "In prostate cancer, MAP3K7 is a putative tumor suppressor gene and MAP3K7 deletion has been shown to directly correlate with prostate cancer progression, lymph node metastasis, and biochemical recurrence." (PMID 32630372, 2020). "Intriguingly, Chd1−/−;Map3k7−/− prostate cancers have neuroendocrine features, consistent with our observation that CHD1 loss can promote expression of aberrant lineage programs." (PMID 32220301, 2020). "CHD1 and MAP3K7 genes are codeleted in 10–20% of prostate cancers and correlated with poor disease-free survival." (PMID 31366128, 2019). "Other gene members of the MAP (mitogen-activated protein) kinase pathway, including MAP3K1 and MAP3K7, have been shown to have recurrent deletions in prostate cancer." (PMID 28423598, 2017). "Our data revealed that MAP3K7 deletion is often heterogeneous in prostate cancer and prevents TMPRSS2:ERG fusion, while TMPRSS2:ERG fusion allows MAP3K7 deletion." (PMID 26684029, 2016). "In summary, the results of this study show that MAP3K7 deletion is often heterogeneous in prostate cancer." (PMID 26684029, 2016). "The data show substantial heterogeneity for MAP3K7 deletion in prostate cancer and suggest that MAP3K7 deletion largely prevents development of TMPRSS2:ERG fusions." (PMID 26684029, 2016). "Loss of MAP3K7 was linked to early PSA recurrence in prostate cancer and was commonly associated with the absence of ERG-TMPRSS2 fusion." (PMID 39796635, 2024). "MAP3K7 deep deletion is a frequent event in prostate cancer, occurring in up to 14.8% of patients." (PMID 32630372, 2020). "However, some studies reported that the deletion of MAP3K7 gene promoted cell proliferation, migration, and invasion in high-grade prostate cancer, as well as induced liver cancer, suggesting the tumor suppressor role of MAP3K7." (PMID 28746466, 2017).
prostate carcinoma (continued). "Notably, prostate cancer is frequently characterized by CHD1 loss, which may explain why certain tumors are inherently permissive to VSV, while those with intact CHD1 or MAP3K7 exhibit resistance." (PMID 41294689, 2025). "However, caution should be taken when pharmacologically inhibiting CHD1 in prostate cancer with SPOP or MAP3K7 deletions, reasoning that CHD1 inhibition may play tumor-promoting roles in these contexts." (PMID 36776288, 2023). "Building on this, another study identified two additional epigenetic factors, MAP3K7 and CHD1, as novel mediators of resistance to oncolytic VSV in prostate cancer." (PMID 41294689, 2025). "Common genetic alterations within the three prostate cancer datasets analyzed were observed in PTEN, DEPTOR, SGK3, FOXO1/3, MAP3K7, RRAGD, SESN1, PIK3CA, PIK3C2B, and PDPK1." (PMID 32630372, 2020). "The frequency of 25.7% MAP3K7 deletions observed by FISH is somewhat higher than in our previous study describing 18.5% MAP3K7 deletions on a TMA containing 2,289 different prostate cancers." (PMID 26684029, 2016). "To thoroughly evaluate the heterogeneity for MAP3K7 deletions and TMPRSS2:ERG fusion status and their interrelationship in prostate cancer, we took advantage of a newly developed heterogeneity tissue microarray (TMA) containing samples from 10 different tumor blocks of 189 large prostate cancers." (PMID 26684029, 2016). "We confirm alterations in six genes previously associated with prostate cancer (MAP3K7, MELK, RCBTB2, ELAC2, TPD52, ZBTB4), and also identify 94 genes not previously linked to prostate cancer progression that would not have been detected using either transcript or copy number data alone." (PMID 26501111, 2015). "For example, MAP3K7 and CHD1 have been shown to be co-deleted in prostate cancer and their co-deletion in ETS rearrangement-negative prostate cancers correlates with poor patient disease-free survival." (PMID 27145457, 2016). "Our screen also identified other stress kinases, including MAP3K7, MAP4K3, and MAPKAPK5 (data not shown), which underscores the critical nature of stress kinase signaling in regulating prostate cancer cell growth." (PMID 22761715, 2012).
breast carcinoma (12 papers, 2015 to 2025). "Furthermore, in breast cancer SF3B1K700E causes a tumor-promoting effect through missplicing in MAP3K7 and downstream activation of NF-κB-signalling." (PMID 37823551, 2023). "EMT marker genes were found to be consistently correlated with MAP3K7 AS across 17 cancer types, indicating that the regulation mechanism is common beyond breast cancer." (PMID 36473963, 2022). "To further confirm the presence of IDR in the protein regions encoded by breast-cancer-associated AS events, we analyzed ADD3, PACSIN2, DIAPH1, MARK3, and MAP3K7 protein sequences with the PONDR web tool, a predictor of natural disordered regions." (PMID 34202984, 2021). "In breast cancer models, MAP3K7 promoted EMT and tumorigenesis, while in other systems it was the knockdown of this gene that promoted EMT." (PMID 27876705, 2016). "Knockdown of MAP3K7 in breast cancer cells inhibited both cell adhesion and invasion and led to reduction of both the incidence and extent of lung metastasis in a mouse model." (PMID 25889255, 2015). "Suppression of MAP3K7 signaling by dominant negative MAP3K7 reduced NF-kB activation in human head and neck squamous cell carcinoma and breast cancer cell lines." (PMID 25889255, 2015). "However, in other cancer types (breast cancer and MDS), alternative splicing in PPP2R5A, MAP3K7, and IRAK4 has been linked to the activation of Akt and NF-κB pathway, TGF-β signaling, and inflammation pathway, respectively." (PMID 40694421, 2025). "Finally, in our functional analysis of aberrantly expressed AS exons in breast cancer cells and tissues (PACSIN2 exon 8, DIAPH1 exon 2, MARK3 exon 16, ADD3 exon 13, and MAP3K7 exon 12), we found that dysregulated cassette exons encode for IDRs." (PMID 34202984, 2021). "Next, we up- or down-regulated the miR-143 level in human breast cancer cell line MCF-7, aiming to explore the effects of miR-143 on cell growth and the expressions of ERK5 and MAP3K7 in BC." (PMID 28746466, 2017). "Furthermore, inhibition of MAP3K7 activity induces cancer cell death in pancreatic and breast cancers, suggesting that MAP3K7 may be an effective target for cancer treatment." (PMID 25889255, 2015). "MAP2K3 and MAP3K7 belong to the MAPK pathway, and activation of the MAPK pathway in breast cancer promotes proliferation, anti-apoptotic influence, and contributes to drug resistance, cancer cell survival, and invasion." (PMID 40426890, 2025). "While some of the top candidates have been previously reported to play a role in cancer (FLNB, MAP3K7, NFYA, and ESYT2) others were identified to be breast cancer-relevant for the first time (NEDD4L, MARK2, ABI1)." (PMID 38664594, 2024). "Downregulation of miR143-3p has also been observed in breast cancer samples; upregulation of this miRNA in the MCF-7 cell line resulted in decreased expression of ERK5 and MAP3K7 proteins, and decreased cell viability." (PMID 36077521, 2022). "Moreover, in breast cancer, dysregulated expression of MAP3K genes, such as MAP3K1 and MAP3K7, promotes tumor growth, invasion, and metastasis through activation of MAPK and NF-κB signaling pathways, mirroring their roles in GC." (PMID 39901302, 2025). "Cell growth assessment performed by MTT assay showed an increase in MAP3K7 expression in breast cancer tissues compared with non-malignant breast tissue." (PMID 34746770, 2021). "Importantly, we were also able to confirm, by RT-PCR, the aberrant AS regulation of PACSIN2, DIAPH1, MARK3, ADD3, MAP3K7, and MARK2 in RNA extracts from two human tumor breast cancer samples tissues and two non-pathological tissues." (PMID 34202984, 2021).
hepatocellular carcinoma (8 papers, 2015 to 2024). A malignant tumor that arises from hepatocytes. "Kinome-wide screening results have revealed that targeting Mitogen-activated protein kinase kinase kinase 7 (MAP3K7) suppressed the proliferation of hepatocellular carcinoma cells in cell culture and tumor xenograft models." (PMID 31387297, 2019). "An additional regulator of MAP3K7 is miR-26b which down-regulates MAP3K7 and inhibits the NF-κB pathway in hepatocellular carcinoma." (PMID 25889255, 2015). "TRIM5 has been reported as a prognostic factor for hepatocellular carcinoma and glioma, which may affect the immune and inflammatory response of virus-infected cells by promoting Lys-63 ubiquitination of MAP3K7/TAK1 complex, but the exact role of TRIM5 in tumors has not been reported." (PMID 38304253, 2023). "For example, in hepatocellular carcinoma (HCC) BIRC3 could promote HCC epithelial-mesenchymal transition (EMT), cell migration and metastasis by upregulating MAP3K7 to induce ERK1/2 phosphorylation." (PMID 38130918, 2023).